RN7SL352P (RNA, 7SL, cytoplasmic 352, pseudogene)
Gene: Miscellaneous RNA gene on chromosome 6 (1,507,322 to 1,507,598, forward strand). Ensembl gene ENSG00000243439.
Homologues: Orthologues: chimpanzee Metazoa_SRP (94% identical), macaque Metazoa_SRP (86% identical). Paralogues in human: RN7SL45P (70% identical), RN7SL1 (69% identical), RN7SL126P (69% identical), RN7SL2 (69% identical), RN7SL820P (69% identical), RN7SL3 (68% identical), RN7SL448P (68% identical), RN7SL178P (67% identical), RN7SL530P (67% identical), RN7SL709P (67% identical), RN7SL769P (67% identical), RN7SL304P (67% identical), and 699 more.